RN7SL187P (RNA, 7SL, cytoplasmic 187, pseudogene)
Gene: Miscellaneous RNA gene on chromosome 9 (121,494,519 to 121,494,821, forward strand). Ensembl gene ENSG00000240299.
Homologues: Orthologues: chimpanzee Metazoa_SRP (99% identical). Paralogues in human: RN7SL2 (83% identical), RN7SL1 (82% identical), RN7SL218P (80% identical), RN7SL3 (80% identical), RN7SL45P (80% identical), RN7SL230P (79% identical), RN7SL322P (79% identical), RN7SL479P (79% identical), RN7SL444P (79% identical), RN7SL44P (79% identical), RN7SL357P (79% identical), RN7SL680P (79% identical), and 702 more.